MTOR (mechanistic target of rapamycin kinase)
Diseases named in the same sentence as MTOR in open-access papers (continued):
Sharing a sentence is not in itself a finding about the gene and the disease.
dermatitis (18 papers, 2019 to 2024). An inflammatory process affecting the skin. "In the following sections, we summarize the relevance of the dysregulated PI3K-Akt-mTOR and associated signaling pathways to certain immune-mediated skin disorders." (PMID 37371141, 2023). "The dysregulation of the PI3K/Akt/mTOR and associated signaling pathways is crucial in the development of chronic immune-mediated cutaneous disorders." (PMID 37371141, 2023). "Taking all this information into account, it is evident that mTOR signaling is implicated in most skin disorders, mainly affecting cell proliferation." (PMID 35163615, 2022). "Natural phytochemicals and synthetic molecules have been extensively tested for their ability to remedy PI3K/Akt/mTOR-associated cutaneous disorders." (PMID 31370278, 2019). "In the microenvironment of dermatitis, the expressions of mTOR, AKT, and c-Jun in HaCaT were increased to about 1.6, 1.73, and 2.0 times, respectively." (PMID 39861084, 2024). "The mTOR signalling and skin inflammation is a complex network and will need further investigation the role of mTOR signalling inhibitors in hyperproliferative skin disorders." (PMID 37275420, 2023). "In the following sections, we discuss recent evidence on the implication of aberrant mTOR signaling in skin diseases, indicating its importance as a common denominator of skin disorders, and suggest potential therapeutic targeting options." (PMID 35163615, 2022). "We envision that untangling these functional implications of mTOR activation during epidermal homeostasis will be critical for developing novel therapies for skin disorders." (PMID 35938153, 2022). "Here, the modulation or inhibition of PI3K/AKT/mTOR signaling resulted in the amelioration of dermatitis, with reduction of epidermal hyperproliferation and skin inflammation." (PMID 34685616, 2021). "In this review, we provide the most recent updates on the role and function of PI3K/AKT/mTOR molecular axis in the pathogenesis of different hyperproliferative skin disorders, and highlights on the current status of preclinical and clinical studies on PI3K-targeted therapies." (PMID 33996865, 2021). "It would also be of interest to investigate whether mTOR inhibition and autophagy induction are promising therapeutic options for skin disorders." (PMID 32784909, 2020). "Therefore, modulating mTOR signaling may provide potential therapeutic opportunities for skin disorders." (PMID 35938153, 2022). "To further investigate the protective mechanisms of PF and PW on skin inflammation and the skin barrier, we examined the effects of PF and PW on the transcriptional levels of key genes in the PI3K/AKT/mTOR signalling pathway." (PMID 36771204, 2023).
Kaposi's sarcoma (18 papers, 2008 to 2026). A malignant neoplasm characterized by a vascular proliferation which usually contains blunt endothelial cells. "Switching from CNIs to mTOR inhibitors has been shown to be associated with regression of post-transplant Kaposi sarcoma." (PMID 28160552, 2017). "Another study found that VDR agonists activate autophagy in Kaposi’s sarcoma cells by inhibiting the PI3K/Akt/mTOR signaling pathway." (PMID 41141390, 2026). "The finding that the mTOR antagonist rapamycin, in contrast to other immunosuppressants, encourages tumor reduction in transplant patients afflicted with KSHV-based Kaposi sarcoma underlines the significance of mTOR signaling cascade in KSHV activity." (PMID 37375460, 2023). "Kaposi’s sarcoma is potentially a good target for mTOR inhibitors, since they are highly vascular tumours and linked directly with HHV-8 viral infection." (PMID 25699174, 2015). "A 66-year old female with HIV-negative classic Kaposi's sarcoma responded to mTOR targeting by rapamycin." (PMID 18509482, 2008). "The same authors stated that the cancer preventing effects of mTOR inhibitors mainly concerns non-melanoma skin cancers and Kaposi sarcomas, both represented just 10% of our underlying malignant diseases." (PMID 37200246, 2023). "Finally, it is important to point out the success reported in the treatment of Kaposi’s sarcoma with mTOR inhibitor conversion in transplant recipients." (PMID 25699174, 2015). "Studies of renal transplant recipients show that use of the immunosuppressant drug rapamycin, an mTOR inhibitor, both prevents and can induce the regression of Kaposi's sarcoma (KS), an opportunistic tumor that arises within a subset of this infected population." (PMID 21264294, 2011). "Conversely, mTOR inhibitors may lower the risk of cancers like non-melanoma skin cancer and Kaposi’s sarcoma." (PMID 41459528, 2025). "mTOR inhibition has been shown to reduce PEL cell survival by interfering with the release of cytokines known to be essential for PEL cell growth, and more recently it has been shown that mTOR inhibition can be effective also against a second KSHV-associated malignancy such as Kaposi's sarcoma." (PMID 25695042, 2015). "Resveratrol has been observed to induce apoptosis in Kaposi sarcoma cells by downregulating the expression of viral FLICE-inhibitory protein (vFLIP) and inhibiting the PI3K/Akt/mTOR pathway, which is frequently hyperactivated in AIDS-defining malignancies." (PMID 41585876, 2025). "In contrast, in the context of Kaposi's sarcoma, Nef and KSHV oncogene K1 synergistically promote angiogenesis by inducing cellular miR-718 to regulate the PTEN/AKT/mTOR signaling pathway." (PMID 30619892, 2018). "However, in Kaposi's sarcoma, Nef in combination with KSHV oncogene K1 synergistically induces cellular miR-718 to regulate the PTEN/AKT/mTOR signaling pathway and thus promotes angiogenesis." (PMID 30619892, 2018). "However, the use of mTOR inhibitors in this indication has only been validated in the context of non-melanoma skin cancers and Kaposi sarcoma, moreover these treatments have lower immunosuppressive effects than CNI and can lead to the increase in proteinuria." (PMID 40590038, 2025).
laryngeal carcinoma (18 papers, 2012 to 2026). Carcinoma that arises from the laryngeal epithelium. "Our previous reported results have demonstrated that expression levels of mTOR and its effectors are associated with the pathological differentiation of laryngeal carcinoma tissues." (PMID 28335497, 2017). "Additionally, fisetin inhibited the activation of PI3K/AKT-controlled mTOR, causing transcription suppression as well as the proliferation inhibition of laryngeal cancer cells." (PMID 36558146, 2022). "In an experiment to evaluate mTOR protein expression in 25 patients with laryngeal carcinoma treated with postoperative radiotherapy, it was found that high expression of mTOR was a prognostic marker for high risk of recurrence after postoperative radiotherapy." (PMID 23762622, 2012). "SPINK5 knockdown enhanced the activity of KLK6 and the activation of the PI3K/AKT/mTOR signaling pathway in laryngeal cancer cells." (PMID 42062847, 2026). "Our study suggests that SLC3A2 regulates ferroptosis and related genes, and therefore subsequently induces laryngeal carcinoma growth and ferroptosis via mTOR signal pathway." (PMID 35057861, 2022). "Collectively, our findings indicate that the PI3K/Akt/mTOR pathway is required for the progression of radioresistance in laryngeal carcinoma Tu212 cells undergoing glycolysis due to hypoxia." (PMID 35415942, 2022). "Our study suggests that SLC3A2 negatively regulates ferroptosis through mTOR pathway in laryngeal carcinoma." (PMID 35057861, 2022). "HIF‐1α and/or Glut‐1 knockout facilitated radiosensitivity in laryngeal carcinoma Tu212 cells by regulation of the PI3K/Akt/mTOR pathway." (PMID 35415942, 2022). "As reported, PI3K/AKT/mTOR participates in fisetin-triggered repression in the growth of laryngeal carcinoma cells." (PMID 34821587, 2021). "Taken together, our findings elucidate that the antitumor effect of PPD is associated with its regulation of mTOR expression and distribution, which encourages further studies of PPD as a promising therapeutic agent against laryngeal carcinoma." (PMID 28335497, 2017). "Taken together, this study unveils an unprecedented correlation of mTOR activation with improved clinical outcome in patients with laryngeal carcinomas and uncovers the potential of p-S6 expression as a good prognostic biomarker and an inverse predictor of lymph node and distant metastases." (PMID 27119232, 2016). "Next, we consider to confirm whether SLC3A2 directly regulates mTOR in laryngeal cancer." (PMID 35057861, 2022). "SLC3A2 deficiency upregulated the expression of mTOR and P70S6K, whereas inhibited p-mTOR and p-P70S6K expression in laryngeal carcinoma cells." (PMID 35057861, 2022). "In this study, IGF‐1 treatment activated PI3K‐Akt‐mTOR signalling pathway, enlarged the resistance to radiotherapy, and elevated glucose uptake and the expression of HIF‐1α and Glut‐1 in laryngeal cancer cells." (PMID 35415942, 2022). "In conclusion, the findings in this study suggest that both the PI3K/Akt/mTOR signalling pathway and HIF‐1α/Glut‐1 are activated in hypoxic tumour cells, thereby facilitating glucose uptake radioresistance in laryngeal carcinoma cells." (PMID 35415942, 2022). "Mechanically, SLC3A2 deficiency facilitated ferroptosis through upregulating the expression of mTOR and P70S6K, whereas inhibited p-mTOR and p-P70S6K expression in laryngeal carcinoma cells." (PMID 35057861, 2022). "Besides, genes from molecular pathways of autophagy (ULK/ATG complex), drug efflux (ABC transporters), mitochondrial activity (V‐ATP synthase), hypoxia (HIF1A), and PI3K/mTOR (PIK3CA, CASTOR1, and DEPTOR) were upregulated in resistant laryngeal cancer cells." (PMID 40385549, 2025). "Finally, some findings recommend that fisetin played a vital task in the regulation of laryngeal cancer by inhibiting the proliferation of tumor cells, the induction of apoptosis as well as autophagy through ERK1/2 and AKT/NF-κB/mTOR signaling pathways." (PMID 36558146, 2022).
metastatic cancer (18 papers, 2013 to 2025). A carcinoma which has spread from the original site of growth to another anatomic site. "Likewise, development of mEAK-7 inhibitors may benefit patients with metastatic cancers that demonstrate aberrant mTOR signaling associated with high levels of mEAK-7." (PMID 31288154, 2019). "Extended endocrine therapy combined with agents, such as cyclin dependent kinase (CDK) inhibitors or mammalian target of rapamycin (mTOR) inhibitors is the most current treatment option for ER+ metastatic cancer." (PMID 32847042, 2020). "For example, mTOR inhibitors have an impact on overall survival of advanced ER+ breast metastatic cancer, but this effect is limited in time." (PMID 28017284, 2017). "The second remarkable finding was that p-mTOR expression was higher in metastatic cancer than in primary cancer of the liver and kidney." (PMID 28831205, 2017). "In cancer tissues, p-mTOR expression was higher in adenocarcinoma than in other types of cancers, in metastatic cancer than in primary cancer, and in the forefront of the infiltrating cancer cells." (PMID 28831205, 2017). "The results from our study may prompt the advancement of PI3K/mTOR inhibitors into clinical trials for patients with advanced metastatic cancer of the CNS from multiple primary origins." (PMID 37215954, 2023). "However, combined treatment with cisplatin and the mTOR inhibitor rapamycin synergistically inhibited cancer stem cell-mediated primary and metastatic cancer growth." (PMID 28915623, 2017). "Stronger membranous and/or cytoplasmic p-mTOR staining in tumor cells at the invasive front and metastatic cancer seen in our study might indicate the involvement of p-mTOR in CSC mobility." (PMID 28831205, 2017). "Interestingly, levels of mTOR-pS2481 are significantly elevated in Alzheimer’s disease (AD) and positively correlated with tau phosphorylation, while phosphorylation of mTOR-S2448 is stronger in metastatic cancer than in primary cancer of liver and kidney." (PMID 33670113, 2021). "In various metastatic cancers, patients treated with PI3K/AKT/mTOR pathway inhibitors in combination with other treatments (ET, anti-HER2 therapy, or chemotherapy) had a longer time to progression compared to patients without PIK3CA mutations." (PMID 38413796, 2024). "Accumulating evidence has suggested that perturbations in the PI3K-Akt-mTOR pathway occur in the vast majority of metastatic cancers; hence, PI3K-Akt-mTOR can be a potential therapeutic target." (PMID 34737700, 2021). "Importantly, early treatment with a PI3K/mTOR inhibitor (dactolisib) prevented the UBE2C-induced leptomeningeal dissemination in these models, revealing a promising therapeutic avenue in advanced metastatic cancer prevention." (PMID 37215954, 2023).
preeclampsia (18 papers, 2014 to 2025). Preeclampsia is a hypertensive disorder of pregnancy that is characterized by new-onset hypertension with proteinuria presenting after 20 weeks of gestation, and depending on mild or severe forms may initially present with severe headache, visual disturbances, and hyperreflexia. "To analyze the effect of L-NG-nitroarginine methyl ester (L-NAME)-induced FGR and associated preeclampsia (PE) on p-mTOR signaling in the placenta, we performed fluorescent immunohistochemical staining using anti-phospho-mTOR (Ser2448) antibody on 13 d.p.c.." (PMID 35163395, 2022). "The relationship between intrauterine insults such as preeclampsia and nutrient restriction, which have previously been associated with altered mTOR signaling in the placenta, have been studied in the RUPP model of preeclampsia and in maternal low-protein diet investigations." (PMID 34828683, 2021). "ADGRE5 promoted trophoblast invasion via the PI3K/Akt/mTOR signaling pathway, which was decreased in preeclampsia patients." (PMID 37501789, 2023). "Thus, further research is needed to verify the regulation role of the mTOR/ERK1/2 signaling/BAK1 axis in preeclampsia." (PMID 37507742, 2023). "Besides, GNG7 silencing promoted the proliferation and differentiation of placental cytotrophoblasts in preeclampsia rats via activating the mTOR signaling pathway." (PMID 33727922, 2021). "Therefore, we inferred that BAK1 might be involved in regulating trophoblast apoptosis of preeclampsia mediated by hsa_circ_0002348/miR-126-3p axis through mTOR/ERK1/2 signaling." (PMID 37507742, 2023). "Here, we also found that activation of FAK-Akt-mTOR mediated signaling in early-onset preeclamptic placentas is significantly decreased, which may be one of the main factors affecting the differentiation and migration of trophoblastic cells in preeclampsia." (PMID 33304321, 2020). "In the gestational hypertension RUPP model, increased beta-cell death, reduced beta-cell area, and decreased mTOR protein level in the offspring fetal pancreas were reported." (PMID 34828683, 2021). "Moreover, there is evidence that mTOR and MAPK pathways are involved in trophoblast biological activity in placenta-mediated pregnancy complications such as fetal growth restriction and preeclampsia." (PMID 37507742, 2023). "Thus, esomeprazole can suppress preeclampsia-like symptoms by inhibiting excessive placental autophagy in PE, acting via the SIRT1/AMPKα-mTOR pathway." (PMID 35091806, 2022).
retinal degeneration (18 papers, 2014 to 2025). Degeneration of the retina. "Inhibition of mTOR signal by rapamycin and its analogs leads to a reduction in the synthesis of misfolded proteins and an increase in the degradation of damaged proteins, which further suppresses the ER stress caused by gene mutations in cases of retinal degeneration." (PMID 28106827, 2017). "It is essential to understand the complicated relationship between the mTOR pathway and oxidative stress before its application in the treatment of retinal degeneration." (PMID 35883796, 2022). "Because of our recent findings suggesting the regulation of p-AKT/p-mTOR by the pseudokinase TRIB3 in mice with inherited retinal degeneration and the TRIB3 upregulation in human and mouse diabetic retinas, we tested the TRIB3 levels as well." (PMID 35046899, 2021). "In line with this, increasing the mTOR activity in a transgenic mouse model was sufficient to induce retinal degeneration." (PMID 34943047, 2021). "In agreement with our findings, RPE-specific mTOR hyperactivation in a transgenic mouse model leads to retinal degeneration, and rapamycin treatment only partially rescued the phenotype." (PMID 34943047, 2021). "In our study, the rd16 mice demonstrated severe retinal degeneration accompanied by p-AKT/p-mTOR downregulation at P15." (PMID 34215725, 2021). "Inhibiting the mTOR signal can normalize metabolic function and alleviate ER stress-induced retinal degeneration." (PMID 28106827, 2017). "Our results showed that mTOR was activated during retinal degeneration induced by MMS, which indicated that the mTOR participated this degeneration process, which may be involved in metabolism or autophagy." (PMID 35295093, 2022). "Although mTOR inhibitors have been recently identified due to their ability to reduce proliferation in cancers, the development of mTORC1 activators that are beneficial for retinal degeneration or other diseases is still a critical need." (PMID 34215725, 2021). "Some preclinical studies have shown a beneficial effect from mTOR inhibition on RPE senescence while others have shown that mTOR physiologically extends photoreceptor survival in animal models of retinal degeneration and mediates the RPE’s response to nerve growth factors." (PMID 30235234, 2018). "In summary, UPR and ER stress are critical factors that contribute to retinal degeneration, yet inhibition of mTOR maintains cellular proteostasis and attenuates ER stress by reducing misfolded protein synthesis and augmenting autophagy to remove misfolded proteins caused by gene mutations." (PMID 28106827, 2017). "Finally, our results further connect several metabolic pathways with retinal degeneration, including insulin, mTOR, and HIF-1 signaling, which in future studies may help to understand the complex mechanisms behind photoreceptor cell death." (PMID 35241647, 2022). "Abnormal mTOR activation in the RPE has been reported in animal models of RPE and retinal degeneration." (PMID 39957408, 2025). "PTEN, an inhibitor of the AKT/mTOR signaling pathway, enables RPE cells to function normally, but the activation of the AKT/mTOR pathway triggers RPE dedifferentiation and retinal degeneration." (PMID 33015046, 2020). "Many previous studies have demonstrated that inhibition of mTOR has neuroprotective effects, including rescue of photoreceptors and or RPE from mutant gene-induced apoptosis, which slow down the process of retinal degeneration." (PMID 28106827, 2017). "Its inhibition of the mTOR pathway could prevent the replicative senescence in cultured RPE cells, while in mouse models of retinal degeneration, rapamycin could prevent photoreceptor dysfunction." (PMID 32012692, 2020). "InR/mTOR signalling acts as a pro-survival pathway preventing retinal degeneration, but its role in mammalian eye development has not been characterised." (PMID 25210733, 2014).
retinal degeneration (continued). "Therefore, understanding the regulation mechanisms of mTOR and S6K1 activities during RP progression might lead to development of therapeutic approaches centered around S6K1 activation for treating patients who suffer from retinal degeneration." (PMID 30442943, 2018).